MICA (MHC class I polypeptide-related sequence A)
Diseases named in the same sentence as MICA in open-access papers (continued):
Sharing a sentence is not in itself a finding about the gene and the disease.
infection (continued). "An increase in MICA surface expression was observed after infection with HCMV ΔUS14-22, while infection with the WT strain led to a complete repression of MICA surface expression." (PMID 28819195, 2017). "One of the key receptors for NK cell activation is NKG2D that has multiple ligands, including MICA, MICB, and ULBP, which are preferentially expressed following cellular stress, infection, or DNA damage." (PMID 27816971, 2016). "During infection, UTI89 showed increased expression of sRNAs responding to envelope stress—MicA, RybB and DsrA." (PMID 26291711, 2015). "Intracellular protein levels of MICA, MICB, ULBP2, and ULBP3 were tested 48 hrs post-infection." (PMID 37753084, 2023). "MICA, MICB, ULBP2, and ULBP3 were upregulated following infection with both HMPV/WT and HMPV/ΔG." (PMID 32698530, 2020). "Since MICA, MICB, and ULBP2 surface levels were significantly higher in cells infected with ΔRh159 compared to RhCMV, we wanted to specifically address the impact of Rh159 on the maturation of these NKG2DLs when newly synthesized during infection." (PMID 27580123, 2016). "MICA molecules are recognized by the NKG2D receptor on the surface of γδ T lymphocytes, CD8+αβ T lymphocytes, and NK cells that contribute to defend the organism against infections, including against infection by M. leprae." (PMID 26793196, 2015). "As the block deletion mutants were made on a ΔUL16ΔUL18 background, the parental HCMV control up regulated MICB and ULBP2 relative to mock-infected cells, whereas the ΔUS18–22 mutant up regulated cell surface levels of MICA relative to both mock- and parental HCMV-infections." (PMID 24787765, 2014). "The down modulation of FR901228-induced MICA/B cell surface expression was detectable 12 hr post infection (data not shown)." (PMID 21857986, 2011). "The inhibition of apoptosis led to a minor increase in FR901228-induced MICA/B surface expression after VSV10 and VSVΔM51 infection, which indicates that apoptosis could be involved in the VSV blockade of HDAC-inhibitor mediated MICA/B expression." (PMID 21857986, 2011). "Likewise, MICA and MICB can be retained in the ER by the adenovirus E3/19K protein following infection." (PMID 21857986, 2011). "VSV is known to cause a global inhibition of translation during infection, however VSV infection did not affect MICA surface expression after transient over expression." (PMID 21857986, 2011). "Presence of MICA in the tracheal epithelial cells and the reduced levels of CD28 in effector CD8+ T cells suggest an essential co-stimulatory role for NKG2D at the site of infection." (PMID 20844584, 2010). "Indeed, semiquantitative RT-PCR analysis of RDAd-infected cells indicated that the levels of MICA/B and ULBP1-3 were all enhanced following RDAd infection of human fibroblasts." (PMID 17374753, 2007). "Importantly, H. pylori WT infection resulted in significantly increased MICA and MICB mRNA levels compared to non-infected cells, and induction increased over time." (PMID 38318189, 2024). "To ascertain if differences in receptor-ligand interactions could be responsible for the impaired capacity of the NK cells to kill the TCD32dim subset, we studied the expression of MICA/B, ULBP-1, CD155, and HLA-E on the surface of HIV-infected CD4+ T cells after ex vivo infection." (PMID 35616530, 2022). "Interestingly, MICA*008 surface levels were upregulated following infection with VarS, but not with BAC2." (PMID 33939764, 2021). "Following infection, ∆Cyto+TM behaved similarly to WT US9, ∆Ig showed partial impairment in MICA*008 downregulation, and 8SP was greatly impaired in MICA*008 downregulation, to the extent that MICA*008 levels in 8SP-expressing cells approached those in EV control cells." (PMID 33824318, 2021).
infection (continued). "In characterising the up regulation of NKG2DL, we identified a differential effect on MICA and MICB by the HCMV IE gene products, and yet HCMV immune evasion functions were effective in preventing surface expression of these NKG2DL through the early phase of lytic infection." (PMID 24787765, 2014). "While infection with a UL16 deletion mutant caused the expected increase in MICB and ULBP2 cell surface expression, deletion of UL142 did not have a similar impact on its target, MICA." (PMID 24787765, 2014). "We set out to determine whether the rapid up regulation of NKG2DL transcription driven by expression of the major HCMV IE genes would result in transient exposure of the activating ligands MICA, MICB, or ULBP2 early during infection, thereby creating a window of opportunity for NK cell recognition." (PMID 24787765, 2014). "Moreover, the FR901228-mediated or the endogenous (data not shown) MICA/B expression on Jurkat T-cells was significantly hampered by VSV10 infection." (PMID 21857986, 2011). "When the 6D4 antibody to MICA/B was used, it could only partially reverse the RDAd vector-induced activation of NK killing (not shown), suggesting that RDAd infection upregulated multiple NKG2D ligands." (PMID 17374753, 2007). "As expected, infection of AGS-MICA transfectants with H. pylori WT or the ΔcagA, ΔcagL and ΔvacA mutants had no significant impact on total MICA mRNA expression and total MICA protein levels in whole cell lysates." (PMID 38318189, 2024). "Shedding of MICA, ULBP2, and ULBP3 was not enhanced post-infection, whereas shedding of MICB was reduced." (PMID 37753084, 2023). "We found no change in CD112, CD155, MICA/B, or CD58 (data not shown) expression following dl922-947 infection." (PMID 32195317, 2020). "Like MYXV, infection with vMyx-M153KO did not affect expression of other NK ligands including HLA–E, MICA/B, ULBP1–3, and PVR (not shown)." (PMID 23762498, 2013). "Combined VSV10 infection and FR901228 treatment led to a further increase in MICA mRNA expression (data not shown)." (PMID 21857986, 2011). "We found that MICA/B expression in CD11b+ cells was only detected in the skin of L. braziliensis patients and not in the blood, suggesting that NKG2D-ligand expression is specific to the skin and not a systemic response to infection." (PMID 37603573, 2023). "MICA and ULBP2 expression were not affected following infection." (PMID 34721381, 2021). "Hence, while some MICA*008 is being degraded via the proteasome, the dominant effect of UL147A (and of US9) during infection appears to be maturation arrest in a non-GPI anchored form." (PMID 33939764, 2021).
infectious disease (6 papers, 2012 to 2021). A disorder directly resulting from the presence and activity of a microbial, viral, or parasitic agent in humans. "Many genes including HLA, KIR, and MICA genes, as well as polymorphisms in cytokines have been investigated for their role in infectious disease." (PMID 23936864, 2013). "MICA alleles are also associated with susceptibility to infectious diseases." (PMID 34650566, 2021). "Another species, C. burnetii, was mainly positively correlated with infectious disease-related genes like RAB2B, MICA, C1QTNF4, and YF6." (PMID 35250914, 2021).
bacterial infection (3 papers, 2014 to 2016). "Polymorphisms in TLR4 and MICA are examples of these changes and have been related to the biology of the inflammatory responses to bacterial infections." (PMID 27559544, 2016). "First, the local immune response in vivo is induced after bacterial infection, resulting in stress-induced expression of MICA." (PMID 26875668, 2016). "A variety of stresses, such as, heat shock and exposure to hydrogen peroxide, DNA damaging agents, or viral or bacterial infection can increase the expressions of MICA/B, although the mechanisms involved remain unclear." (PMID 24512718, 2014).
hematological cancer (2 papers, 2016 to 2018). "Further experiments will be needed to better investigate the role of CBP/EP300 as a regulator of MICA gene expression in patient-derived MM cells and in other hematological tumors." (PMID 27903272, 2016).
digestive system cancer (1 paper, 2017). A primary or metastatic malignant neoplasm involving any part of the digestive system. "With regards to MICA/B expression as detected by IHC, high MICA/B expression level was associated with longer survival in cancers of the digestive system." (PMID 29221214, 2017). "However, the association between MICA/B expression and survival was significant for digestive system cancers (P = 0.002)." (PMID 29221214, 2017).
inflammation (1 paper, 2019). Aberrant reaction of the microcirculation characterized by movement of fluid and leukocytes from the blood into extravascular tissues. "We next assessed the association between MICA rs2596542 and DEPDC5 rs1012068 and liver damage (hepatic inflammation and fibrosis)." (PMID 30723271, 2019).
neurodevelopmental disorder (1 paper, 2023). A behavioral and cognitive disorder with onset during the developmental period that involves impaired or aberrant development of intellectual, motor, or social functions. "For example, a 96.8-Kb deletion was found in two unrelated ASD patients (#8 and #127) at 6p21.33, which disrupts the major histocompatibility complex (MHC) class I gene MICA, which was not previously implicated with broader neurodevelopmental disorder patients." (PMID 36959829, 2023).
MICA also shares sentences with these, for which no sentence is quoted: uveal melanoma (4 papers); adenocarcinoma (3); chronic lymphocytic leukemia (3); lung adenocarcinoma (3); multiple sclerosis (3); Addison's disease (2); agranulocytosis (2); Alzheimer disease (2); bipolar disorder (2); chronic hepatitis (2); gestational diabetes (2); Graves disease (2); head and neck squamous cell carcinoma (2); Kawasaki disease (2); kidney (2); mesothelioma (2); Primary Sjögren’s Syndrome (2); renal carcinoma (2); Stroke (2); (CIN) III (1); acute chest syndrome (1); allergic asthma (1); aplastic anemia (1); atopic dermatitis (1); CADASIL (1); carcinoma in situ (1); cervical intraepithelial neoplasia (1); cholelithiasis (1); cholestatic jaundice (1); chronic cervicitis (1).
A further 41 diseases each share a sentence with MICA in 1 paper.